RAB3B (RAB3B, member RAS oncogene family)
Diseases named in the same sentence as RAB3B in open-access papers (continued):
Sharing a sentence is not in itself a finding about the gene and the disease.
lung adenocarcinoma (continued). "We also reveal an interaction between Rab3B and DDX6, which contribute to the aggressive phenotype in lung adenocarcinoma cells both in vitro and in vivo." (PMID 38834947, 2024). "Rab3B interacts with and stabilizes DDX6 protein to accelerate lung adenocarcinoma progression." (PMID 38834947, 2024). "Given the interaction between Rab3B and DDX6, we speculated that DDX6 might be involved in lung adenocarcinoma progression." (PMID 38834947, 2024).
brain tumor (1 paper, 2024). "Protein expression analysis revealed a significant decrease in RAB3B protein expression levels in brain tumor, COAD and PDAC compared to normal samples." (PMID 38688977, 2024). "Utilizing the cProSite visualization tool, we observed a significant downregulation of RAB3B gene expression in brain tumor samples compared to normal tissues." (PMID 38688977, 2024).
cervical cancer (1 paper, 2020). A primary or metastatic malignant neoplasm involving the cervix. "Three genes (COPE, RAB3B, and TFPI) in the network were significantly associated with overall survival (P < 0.05), which indicated that these genes could act as prognostic biomarkers for patients with cervical cancer." (PMID 33330502, 2020). "Analysis of a TCGA dataset revealed that a total of 3 target genes (COPE, RAB3B, and TFPI) in the regulatory network were correlated to survival curves with clinically significant outcomes in cervical cancer." (PMID 33330502, 2020).
glomerular disease (1 paper, 2023). "Recently, single-cell RNA sequencing revealed that RAB3B was downregulated in glomerular disease or podocyte injury models, and knockdown of RAB3B resulted in significant loss and rearrangement of F-actin stress fibers, consistent with our results in the present study." (PMID 36792603, 2023).
hypopharyngeal cancer (1 paper, 2022). Carcinoma, predominantly squamous cell, arising from the epithelial cells of the hypopharynx. "Then, we built PDOs from human tissue of hypopharyngeal cancer patients, and the expression level of RAB3B was higher in cancer tissues than in adjacent normal tissues." (PMID 35194030, 2022).
laryngeal squamous cell carcinoma (1 paper, 2020). A squamous cell carcinoma that arises from the larynx. "Previous studies have reported the overexpression of RAB3B in various types of cancer, such as laryngeal squamous cell carcinoma and lung squamous cell carcinoma." (PMID 33330502, 2020).
lung carcinoma (1 paper, 2024). "CREB protein was enriched at the promoter of Rab3B in lung cancer cells." (PMID 38834947, 2024). "ChIP assays validate that CREB protein is enriched at the promoter of Rab3B in lung cancer cells." (PMID 38834947, 2024). "Despite these findings, it remains unclear whether Rab3B could modulate lung cancer cell behaviors." (PMID 38834947, 2024).
Neuroepithelial Tumor (1 paper, 2024). "Using the cBioPortal platform for analyzing gene and expression data from various cancers, we found that RAB3B had mutations in most cancers, with the highest mutation rate in Ovarian Epithelial Tumor, Miscellaneous Neuroepithelial Tumor, and Sarcoma." (PMID 38688977, 2024). "Interestingly, in Miscellaneous Neuroepithelial Tumor, the mutation type of RAB3B is Deep Deletion." (PMID 38688977, 2024).
pituitary adenoma (1 paper, 2017). "RAB3B, a key exocytosis regulator in anterior pituitary cells, has been demonstrated by immunohistochemistry staining to be overexpressed in pituitary adenoma." (PMID 28784136, 2017).
uterine cancer (1 paper, 2024). Primary or metastatic malignant neoplasm involving the uterine corpus and/or the cervix. "Conversely, RAB3B gene expression was significantly upregulated in tumor samples of HNSC, LIHC, LUAD, LUSC, PDAC, and Uterine Cancer compared to normal samples." (PMID 38688977, 2024).
Vertigo (1 paper, 2022). An abnormal sensation of spinning while the body is actually stationary. "The eQTL-based TWAS identified 99 cis-regulated expression genes associated with vertigo, such as RAB3B (PTWAS = 0.017), TMEM132E (PTWAS = 0.002), and TCEA3 (PTWAS = 0.037)." (PMID 36519156, 2022). "In particular, RAB3B was detected to be associated with vertigo in two independent PWASs and eQTL-based TWAS, which strongly suggested that RAB3B might be a vital risk gene for vertigo." (PMID 36519156, 2022). "Our study suggesting that RAB3B and MTERFD2 are highly risk genes whose expression and protein abundance are significantly associated with vertigo." (PMID 36519156, 2022). "Compared with TWAS results, we identified overlapping genes RAB3B (PTWAS = 0.017) and MTERFD2 (PTWAS = 0.003) that showed significant associations with vertigo at both proteome-wide and transcriptome-wide levels." (PMID 36519156, 2022). "They provide novel genes (MTERFD2, MGST1, and RAB3B) into the pathogenesis of vertigo, and highlight promising chemicals for further therapeutics research." (PMID 36519156, 2022). "In conclusion, we identified three high-confidence genes (RAB3B, MTERFD2, and MGST1) showed proteome-wide significant associations in the human brain with vertigo in two independent brain proteomes, strongly highlighting the underlying pathogenesis of these proteins in vertigo." (PMID 36519156, 2022). "Importantly, three common vertigo risk genes showed proteome-wide significant signals in both discovery and replication stages, including MTERFD2 (PBanner = 0.045, PROSMAP = 0.031), MGST1 (PBanner = 0.014, PROSMAP = 0.018), and RAB3B (PBanner = 0.045, PROSMAP = 0.035)." (PMID 36519156, 2022).
cancer (15 papers, 2014 to 2025). A tumor composed of atypical neoplastic, often pleomorphic cells that invade other tissues. "RAB3B exhibited significant associations with immune inhibitory/stimulatory genes listed in pan-cancer." (PMID 38688977, 2024). "Compared with other relevant studies, our study revealed the multiple roles of RAB3B in cancer, not only at the levels of gene mutation and expression but also with regards to its influence on methylation." (PMID 38688977, 2024). "In most cancer types, we identified RAB3B mutations that showed a significant correlation with tumor mutational burden (TMB), mutant-allele tumor heterogeneity (MATH), and microsatellite instability (MSI)." (PMID 38688977, 2024). "This study discovered a notable association between RAB3B and presently listed genes that either suppress or enhance the immune response in various types of cancer." (PMID 38688977, 2024). "We discovered a strong association between the expression of the RAB3B gene and the level of immune cell infiltration in various types of cancer, specifically in COAD and THCA." (PMID 38688977, 2024). "As reported in this study, we found that the overexpression of RAB3B in 11 types of cancer was associated with a certain degree of diagnostic accuracy, especially in GBM, where the AUC value was close to 1, indicating its potential diagnostic value." (PMID 38688977, 2024). "RAB3B expression has been associated with several cancer cells, where the silencing of RAB3B significantly inhibits cell proliferation and promotes apoptosis." (PMID 36232712, 2022). "miR-3158-5p was negatively associated and RAB3B was positively associated with cancer stage, while NEAT1 was positively associated with cancer stage, but without statistical significance." (PMID 35664777, 2022). "miR-3158-5p was negatively associated and RAB3B was positively associated with cancer stage, while NEAT1 was positively associated with cancer stage, but without statistical significance (–G)." (PMID 35664777, 2022). "Given the induction of Rab3B upon LKB1 loss, we suggest that Rab3B may function as an oncogenic driver in LKB1-deficient cancers." (PMID 38834947, 2024). "Furthermore, we have also discovered a notable association between the expression of RAB3B and several cancer-related indicators, such as TMB, MATH, and MSI." (PMID 38688977, 2024). "The findings suggest that RAB3B may be associated with the progression of specific subtypes of cancer." (PMID 38688977, 2024). "In addition, we have identified mutations in RAB3B in most cancers, and its expression levels are significantly associated with cancer-related indicators such as TMB, MATH, and MSI." (PMID 38688977, 2024). "Furthermore, RAB3B was upregulated and miR-3158-5p was downregulated in GC tissues compared with adjacent normal tissues, which was also associated with cancer stage." (PMID 35664777, 2022). "As spheroid formation is an important feature of cancer stemness, we investigated the expression of stemness markers and RAB3B between tumorspheres and adherent non‐sphere cells." (PMID 40135815, 2025). "Our findings indicate that elevated RAB3B expression can independently predict prognosis in many tumors and has moderate accuracy for diagnosing most cancers." (PMID 38688977, 2024). "Through our analysis of various types of cancer, we have gained a thorough comprehension of how RAB3B contributes to their development, broadening the possibilities for utilizing RAB3B in the treatment of cancer." (PMID 38688977, 2024). "In these two types of cancer, RAB3B expression exhibited a positive correlation with all six categories of immune cell infiltration." (PMID 38688977, 2024). "Our analysis of a larger sample size has yielded more comprehensive insights into the role of RAB3B in the mechanisms of cancer development, surpassing previous studies." (PMID 38688977, 2024).
cancer (continued). "Developing new cancer therapies can therefore be improved by studying RAB3B's molecular mechanisms and regulatory functions in pan-cancer datasets." (PMID 38688977, 2024). "We also investigated the relationship between RAB3B expression and 60 immune checkpoint pathway genes in pan-cancer." (PMID 38688977, 2024). "Our study found changes in the methylation of RAB3B in 13 types of cancer tissues, indicating the universality of abnormal methylation in various cancers." (PMID 38688977, 2024). "By analyzing TCGA and GTEx databases, comprehensive analyses of RAB3B expression in pan-cancer datasets were performed." (PMID 38688977, 2024). "The provided data offers valuable understanding of the involvement of RAB3B in the development of cancer and holds significant implications for the creation of innovative treatment approaches." (PMID 38688977, 2024). "To examine the potential involvement of RAB3B in the development of cancer, we analyzed data from various sources including The Cancer Genome Atlas (TCGA), Genotype-Tissue Expression Project (GTEx), cBioPortal, HPA, UALCAN, and tissue microarray (TAM)." (PMID 38688977, 2024). "To further validate the expression of RAB3B in different cancers, we selected TMA and used IHC staining to assess the expression of RAB3B." (PMID 38688977, 2024). "Based on our pan-cancer analysis, we found significant differences in RAB3B expression between most cancerous and normal tissues, and a correlation between RAB3B expression and clinical outcome." (PMID 38688977, 2024). "In 29 out of 32 cancer types, we observed a significant correlation between RAB3B expression and immune infiltration." (PMID 38688977, 2024). "Our analysis focused on exploring the expression levels and prognostic significance of RAB3B in pan-cancer." (PMID 38688977, 2024). "The IHC results revealed that the expression of RAB3B in six types of tumors was consistent with the results of the pan-cancer analysis of the database." (PMID 38688977, 2024). "For this research, we employed data from databases like TCGA and GTEx to perform a comprehensive examination of RAB3B across various types of cancer." (PMID 38688977, 2024). "There is also a significant correlation between RAB3B expression and immune scores in various types of cancers, as well as a significant positive correlation between RAB3B expression and CD276 in 22 types of cancer." (PMID 38688977, 2024). "Further examination of the CPTAC and HPA databases confirmed the variations in protein expression of RAB3B across multiple cancer types." (PMID 38688977, 2024). "Using bioinformatics techniques, we examined the correlation between RAB3B expression and prognosis, tumor heterogeneity, methylation modifications, and immune microenvironment across different cancer types." (PMID 38688977, 2024). "It is evident that RAB3B protein expression is significantly elevated in 10 types of cancer when compared to normal tissues." (PMID 38688977, 2024). "The precision and reliability of these findings offer an important contribution to the current body of research on RAB3B and its potential as a viable therapeutic target for cancer treatment." (PMID 38688977, 2024). "The next step will be to collect more samples and perform more detailed analyses to better understand the mechanisms of RAB3B in cancer." (PMID 38688977, 2024). "According to the perspective of pan-cancer, a thorough evaluation was conducted on the expression levels of RAB3B at different clinical and pathological stages." (PMID 38688977, 2024). "Through pan-cancer analysis, we observed significant differences in RAB3B expression levels between tumors and normal tissues, making it a potential primary factor for cancer diagnosis and prognosis." (PMID 38688977, 2024). "We investigated the expression differences of RAB3B gene and protein in selected cancers by analyzing the CPTAC database." (PMID 38688977, 2024).
cancer (continued). "For example, RAB3B, a gene encoding a small GTP-binding protein that was reported to play a significant role in a variety of cancers, was strongly expressed from amplified eccDNA." (PMID 35194030, 2022). "RAB3B-KD and its constitutive rescued cells were generated and used to examine the effects of RAB3B on the cancer stem-like phenotype." (PMID 35277124, 2022). "There has been an increase in research on RAB3B's relevance to cancer over the past few years." (PMID 38688977, 2024). "Furthermore, by conducting a collaborative examination of the GTEx database's data on samples from healthy individuals, we have identified a notable disparity in the expression of RAB3B between cancerous and healthy tissues across 29 different cancer types." (PMID 38688977, 2024). "In addition, we investigated how RAB3B correlates with pan-cancer immune scores in the tumor microenvironment (TME)." (PMID 38688977, 2024). "However, understanding of RAB3B’s involvement in carcinogenesis is mostly limited to specific cancer subtypes." (PMID 38688977, 2024). "Research on RAB3B in cancer, however, is mostly confined to specific types." (PMID 38688977, 2024). "We found that high expression of RAB3B is moderately accurate in diagnosing most cancers, and may serve as an independent prognostic factor in many cancers." (PMID 38688977, 2024). "In closing, these findings support the notion that RAB3B may hold considerable prognostic worth in cancer and provide beneficial guidance for actual medical treatments." (PMID 38688977, 2024). "Additionally, we found significant correlations between RAB3B expression, immune cell infiltration, and immune scores across various cancers." (PMID 38688977, 2024). "Therefore, by systematically studying the potential connections between RAB3B expression, immune cell infiltration, immune checkpoints, and immune scoring in pan-cancer, new strategies and targeted therapies can be provided for cancer treatment." (PMID 38688977, 2024). "Multivariate Cox-proportional hazard model analysis was first conducted using hsa-mir-1247-3p, KIF20A, RAB3B, ORC1L, and DLGAP5 expression, MDSC, Th2, and HSC infiltration, LUAD cancer patient age and cancer stage as covariates to identify key markers promoting loss of patient survival rate." (PMID 37948380, 2023). "Although the role of RAB3B in cancers is largely unknown, urinary exosomes in patients with prostate cancer reportedly contain high amounts of this protein." (PMID 35277124, 2022). "In addition to neuronal/secretory cells, Rab3B is also found in cancer cells." (PMID 38834947, 2024). "Hence, additional investigation on the manifestation of RAB3B in comprehensive cancer datasets and its possible links to tumor diversity, alterations in methylation, and the immune microenvironment may offer novel avenues for clinical cancer therapy." (PMID 38688977, 2024). "Hence, exploring RAB3B's regulatory roles and molecular mechanisms through comprehensive cancer datasets might offer innovative approaches for managing clinical cancer." (PMID 38688977, 2024). "The potential relationship between RAB3B and CD276 can act as a unique potential target for cancer immunotherapy." (PMID 38688977, 2024). "Specifically, Rab3B interacts with and potentiates the stability of DDX6, which endows cancer cells with more aggressiveness." (PMID 38834947, 2024). "Due to their likely role in promoting cancer progression, ORC1L, KIF20A, DLGAP5, and RAB3B were selected as marker genes for downstream analysis." (PMID 37948380, 2023). "Consistent with results obtained from the TCGA-COAD cohort, six CRGs, including DPP7, GPRASP1, UNC5C, RAB3B, PCDH9, SLC18A2, were significantly downregulated, whereas CDR2L was upregulated in cancer tissues in comparison with paracancerous normal tissues." (PMID 37384293, 2023).
cancer (continued). "With the exception of cancers lacking normal tissue data or having very limited normal samples, the expression of RAB3B in 16 cancers was found to be markedly distinct from that in normal tissues." (PMID 38688977, 2024). "RAB3B, a member of the small GTP-binding protein RAB family that is involved in cell autophagy and drug resistance, has been reported as an important oncogene in various cancers." (PMID 35194030, 2022).